ENSG00000280571 (novel protein)
Gene: Protein-coding gene on chromosome 3 (42,705,756 to 42,804,518, reverse strand). Ensembl gene ENSG00000280571.
Genetic constraint (gnomAD): Loss-of-function variants: 67 observed, 91.49 expected, observed/expected ratio (o/e) 0.73, 90% interval 0.6 to 0.9. Missense variants: 842 observed, 919.71 expected, observed/expected ratio (o/e) 0.92, 90% interval 0.86 to 0.97. Synonymous variants: 322 observed, 375.76 expected, observed/expected ratio (o/e) 0.86, 90% interval 0.78 to 0.94.